CTLA4 (cytotoxic T-lymphocyte associated protein 4)
Diseases named in the same sentence as CTLA4 in open-access papers (continued):
Sharing a sentence is not in itself a finding about the gene and the disease.
tumor (continued). "Tregs, recruited by tumor‐derived chemokines, suppress DC immunogenicity through multiple mechanisms, including CTLA‐4‐mediated downregulation of CD80/CD86, induction of IDO expression, and secretion of inhibitory cytokines." (PMID 40667699, 2025). "The critical genes high/low expression groups of tumor samples showed different immune responses towards PD-1, PD-L1, and CTLA-4 immunotherapy." (PMID 41007849, 2025). "While the MUC1-based mRNA vaccine elicited an antigen-specific cytotoxic T-cell response and enhanced T-cell infiltration into the tumor, the combination with CTLA-4 siRNA appeared to enhance this effect." (PMID 40943370, 2025). "IL6 further upregulates immune checkpoint molecules such as PD1 and CTLA4 on CTLs, promoting tumor immune evasion." (PMID 40427188, 2025). "It will be interesting in future studies to perform single-cell RNA sequencing (scRNA-seq) analysis to further characterize the molecular mechanisms involved in the remodeling of tumor endothelial cells during anti-CTLA-4 therapy." (PMID 40460830, 2025). "ICI enhance the anti-tumor activity of T cells by blocking the PD-1/PD-L1 or CTLA-4 pathway, thereby relieving immunosuppression." (PMID 40356915, 2025). "Clinical trials have shown that targeted molecules such as CTLA-4 and PD-1 in cancer patients can restore the anti-tumor immune response." (PMID 39958358, 2025). "Altogether, our results indicate that anti-CTLA-4 antibodies remodel tumor vasculature and increase TA-HEVs through Fc-dependent mechanisms." (PMID 40460830, 2025). "By inhibiting the PD-1/PD-L1 and CTLA-4 pathways, ICIs enhance T-cell-mediated anti-tumor immunity but can also lead to immune dysregulation, resulting in irAEs such as IMLI." (PMID 40881884, 2025). "As a novel immune checkpoint protein, LILRB’s ITIM structure, similar to CTLA-4 and PD-1, can be directly expressed on the surface of tumor cells, participating in tumor cell growth and survival." (PMID 40242768, 2025). "In a breast tumor model, it was found that metformin combined with anti-CTLA4 treatment leads to significant improvements in tumor burden, survival rate, and CTL activity." (PMID 40087690, 2025). "The approved CTLA-4 blockers for various tumor treatments include ipilimumab (approved in 2011) and tremelimumab (approved in 2022, combined therapy with durvalumab)." (PMID 40006624, 2025). "The CTLA-4 pathway also plays a role in regulating anti-tumor immunity, and its combination with PD-1 inhibitors has shown promising therapeutic potential." (PMID 41228276, 2025). "Combining low-dose cyclophosphamide (CTX) with anti-CTLA-4 resulted in significant tumor growth inhibition, although sequential treatment with gemcitabine yielded the most significant antitumor effect." (PMID 40281554, 2025). "Blocking CTLA-4 with monoclonal antibodies such as ipilimumab or tremelimumab can reverse this inhibition and trigger anti-tumor immune responses." (PMID 41007256, 2025). "Tremelimumab is a cytotoxic T-lymphocyte-associated protein 4 (CTLA-4)-targeted humanized IgG2 monoclonal antibody, which inhibits tumor growth by preventing the interaction between CTLA-4 and B7s and thereby allowing T-cell activation." (PMID 40405250, 2025). "As a result, these changes boost the anti-tumor immune response and increase the effectiveness of ICIs, such as anti-CTLA4 antibodies." (PMID 40860838, 2025). "In the TME, tumor cells often suppress the activity of T cells through immune checkpoint pathways, such as PD-1/PD-L1 and CTLA-4, thereby evading immune surveillance." (PMID 40094019, 2025). "Combining OVs with ICIs, including anti-PD-1, anti-PD-L1, and anti-CTLA-4 antibodies, further amplifies T cell-mediated tumor clearance by exploiting VSV-induced immunogenic cell death, improving therapeutic outcomes." (PMID 41294689, 2025).
tumor (continued). "A significantly elevated expression of checkpoint inhibitors was detected in Cluster two tumours, including PD-1, PD-L1, CTLA4, CD80/CD86 costimulatory molecules, and emerging targets like TIGIT and LAG3." (PMID 41050056, 2025). "Therapeutic blockade of PD-1 and CTLA-4 has demonstrated significant efficacy in reinvigorating exhausted T-cells and enhancing anti-tumor responses." (PMID 40860882, 2025). "One of the most promising strategies to counteract tumor-induced immunosuppression is the combination of γδT cell therapy with immune checkpoint inhibitors (ICIs) targeting PD-1, PD-L1, or CTLA-4." (PMID 40226616, 2025). "Agents such as QL1706, MEDI5752, and cadonilimab are designed to simultaneously target PD-1 and CTLA-4 in a tumor-selective manner or optimized molecular formats, potentially reducing systemic toxicity without compromising efficacy." (PMID 41013723, 2025). "Bayesian deconvolution and machine learning techniques were applied to investigate tumor progression, prognosis, and immune-epithelial cell interactions, particularly focusing on immune checkpoint markers such as PD-L1 and CTLA-4." (PMID 39992528, 2025). "miRNAs also regulate immune checkpoints (e.g., PD-L1 and CTLA-4), metabolic reprogramming, and stress responses that collectively influence tumor immunogenicity." (PMID 40647470, 2025). "Inhibitory molecules such as PD-1, LAG3, and CTLA4 on Treg cells serve important roles in suppressing the activation of nearby immune cells and represent perturbation targets to unleash anti-tumor immunity." (PMID 40468052, 2025). "As a complement to this, the potential compromise of immune responses in chronic liver disease was assessed by treating tumour‐bearing animals with anti‐PD‐1/CTLA‐4 immunotherapy." (PMID 40760842, 2025). "We concluded that anti-CTLA-4 antibodies prune tumor endothelial cells and upregulate the PD-L1 immune checkpoint on TA-HEVs via Fc- and IFNγ-dependent mechanisms." (PMID 40460830, 2025). "Combination ICIs (such as anti-PD-1, PD-L1, and CTLA-4) with tumor vaccines enhances antitumor immunity through IFN-γ-mediated recruitment of peripheral immune effectors into tumor lesions." (PMID 40661781, 2025). "One way tumor cells evade the immune system is through CTLA-4 and PD-1 pathways; thus, these agents ultimately work by inhibiting the tumor cell's ability for evasion." (PMID 40686734, 2025). "Overall, PD-1 blockade demonstrates greater tumor specificity and results in fewer severe side effects, while CTLA-4 blockade induces more extensive immune activation and increased incidence of immune-related toxicities." (PMID 40514725, 2025). "Currently, PD-1 and cytotoxic T-lymphocyte-associated antigen 4 (CTLA-4) are two well-characterized and extensively studied in the DLBCL tumor immune microenvironment." (PMID 40231264, 2025). "In melanoma models, to some extent, increased immune activity after anti-CTLA-4 treatment improved tumor prognosis." (PMID 40216744, 2025). "When combined with the CTLA‐4 antibody ipilimumab or administered postsurgery, this approach has resulted in durable tumor responses in patients." (PMID 40667699, 2025). "CTLA‐4 inhibitors can also enhance the anti‐tumor response by inhibiting CTLA‐4 from competing with CD28 for binding to B7‐1 and B7‐2, thereby promoting T cell activation." (PMID 41531782, 2025). "Antibodies targeting “Programmed Cell Death Protein-1 (PD-1), Programmed Cell Death Ligand-1 (PD-L1), and Cytotoxic T-Lymphocyte-Associated Protein 4 (CTLA-4)” restore T-cell activity, allowing the immune system to identify and destroy tumours." (PMID 40265416, 2025). "CTLA-4 primarily acts in the early stages of T-cell activation within lymphoid organs, whereas PD-1/PD-L1 functions at later stages, mainly within the tumor microenvironment." (PMID 40842533, 2025). "ICIs inhibit molecules like CTLA-4, PD-1, or PD-L1, freeing the immune system from suppression and activating immune cells to boost the anti-tumor response." (PMID 40242775, 2025).
tumor (continued). "Mechanistically, PD-1/PD-L1 interaction facilitates tumor immune evasion through T-cell anergy induction, while CTLA-4 modulates early T-cell activation via competitive CD80/86 binding." (PMID 40963599, 2025). "In recent years, tumor immunotherapy has advanced significantly with the introduction of immune checkpoint inhibitors such as PD‐1 and CTLA‐4." (PMID 39673181, 2025). "The result from this single case preliminarily supports the potential of cadonilimab, as a PD-1/CTLA-4 bispecific antibody, to induce deep tumor remission." (PMID 41561746, 2025). "Combination therapy with anti-PD-1 and anti-CTLA-4 antibodies reduced tumor growth in 4T1 BC models." (PMID 40281554, 2025). "In particular, CTLA-4 inhibition has been associated with an increase in T cell factor-1 (TCF-1)+ memory progenitor CD8+ T cells, which are crucial for sustained anti-tumor immune surveillance and preventing relapse." (PMID 41013723, 2025). "Inhibiting USP5, along with Trametinib or anti-CTLA-4 treatment, shows an additive effect in inhibiting tumor growth in mice." (PMID 40040703, 2025). "In another study, Tremelimumab, an immunoglobulin G2 (IgG2) monoclonal antibody that targets CTLA-4, was administered to 21 patients with HCV-associated HCC at around 15 mg/kg every three months until the tumor progressed." (PMID 40869156, 2025). "Combining ICIs with chemotherapy has shown synergistic anti-tumor effects, supporting the rationale for combining chemotherapy with dual immune checkpoint blockade (anti-CTLA-4 and anti-PD-1) in solid tumors." (PMID 40070819, 2025). "These agents target key regulatory pathways, such as cytotoxic T-lymphocyte-associated protein 4 (CTLA-4), programmed cell death protein 1 (PD-1), and its ligand PD-L1, to overcome tumor-induced immune suppression." (PMID 40642076, 2025). "Preclinical studies demonstrated that HT therapy synergized with CTLA-4 blockade to elicit potent anti-tumor effects, significantly reducing local and distant tumor growth compared to monotherapy or untreated controls." (PMID 40281554, 2025). "Others characterized an in situ crosslinked hydrogel for the prolonged release of antibodies that simultaneously target CTLA-4 and PD-1 signaling at the tumor site." (PMID 40136857, 2025). "As a result, current research is focusing on combining anti-PD-1 therapy with other immunotherapeutic approaches, such as CTLA-4, tumor vaccines, or adoptive T-cell therapies, in an effort to improve treatment efficacy in GBM." (PMID 40223032, 2025). "Tumor growth ratio (day 25 tumor volume vs. day 10 tumor volume) analysis further showed a significant reduction of tumor progression in both the rAd.sT.GM + anti-CTLA-4 group, and the triple treatment group compared with the control group." (PMID 40104170, 2025). "Others reduce immunosuppression in the tumor environment, for example by using immune-checkpoint inhibitors (such as anti-PD-1, anti-PD-L1 and anti-CTLA4 antibodies)." (PMID 40809017, 2025). "PBMCs combined with anti-BTLA plus anti-CTLA-4 or anti-PD-1 Ab had significant tumor-killing ability in vitro." (PMID 41011166, 2025). "CTLA-4 inhibitors exert anti-tumor effects by preventing Tregs from down-regulating CD80/86 expression and depleting Tregs through antibody-dependent cell-mediated cytotoxicity (ADCC) and phagocytosis (ADCP)." (PMID 40356928, 2025). "When these signals are blocked, e.g., by ipilimumab targeting CTLA-4, or nivolumab and pembrolizumab targeting PD-1, T-cells remain active, proliferate, secrete cytokines and induce lysis of tumor cells." (PMID 41374974, 2025). "An EPS from lactobacilli strains has been reported to increase CCR6+ CD8+ T-cell populations in Peyer’s patches, supporting their migration to CCL20-expressing tumor sites and thereby boosting the effects of immune checkpoint blockades (e.g., anti-CTLA-4 mAb)." (PMID 41301527, 2025).
tumor (continued). "Anti‐CTLA‐4 antibody has been successfully applied in cancer immunotherapy, and it has been suggested that the anti‐tumor role of CTLA‐4 is dependent on different Bacteroides species, which play a vital function in CTLA‐4‐blocked immune stimulation." (PMID 40060755, 2025). "Activated Tregs suppress Mreg DCs via CTLA-4 and migrate to draining lymph nodes, thereby limiting tumor antigen presentation and impeding the initiation of anti-tumor adaptive immune responses." (PMID 41346579, 2025). "ICIs, like anti-PD-1 and anti-CTLA-4, complement therapeutic vaccines by expanding tumor-specific T-cell populations and preventing immune exhaustion." (PMID 40430901, 2025). "The PD1/CTLA‐4 BsAb significantly improves tumor suppression, boosts CD8+ T cell immune responses, and reduces adverse events, offering a promising strategy for more effective cancer treatment." (PMID 39606809, 2025). "Two major proteins, programmed cell death protein 1 (PD-1) and cytotoxic T lymphocyte-associated protein 4 (CTLA-4), function as master controllers of T cell activation, maintaining immune homeostasis while determining the fate of anti-tumor responses." (PMID 41463504, 2025). "One of the well-known factors to lead tumor immune escape is increased expression of immune checkpoint molecules mediating co-inhibitory signals such as PD-1, CTLA-4, LAG3, TIM-3 in T cells, so-called T cell exhaustion." (PMID 39952933, 2025). "The fact that only a subset of patients responds to available ICIs, mainly targeting PD-1/PD-L1 and CTLA-4 axes, highlights the importance of the other ICPs in mediating tumor cells' immune evasion." (PMID 41233805, 2025). "On the contrary, M2-type TAMs suppress T cell-mediated anti-tumor immunity through multiple signaling pathways, including the CD86/cytotoxic T-lymphocyte associated protein 4 (CTLA4) and secreted phosphoprotein 1 (SPP1)/CD44 pathways." (PMID 40600065, 2025). "ICIs work by blocking inhibitory immune checkpoints, such as PD-1/PD-L1 and CTLA-4, which restores the ability of T cells to detect and destroy tumor cells." (PMID 40943541, 2025). "While direct evidence of DN T cells in canine tumors is limited, their immunoregulatory properties in tissues and the clinical activity of CTLA4-targeted therapies in dogs support a potential functional role within the tumor microenvironment." (PMID 41488614, 2025). "By targeting tumor-associated antigens, such as CD33 or EGFR, while simultaneously inhibiting checkpoint pathways like PD-1/PD-L1 or CTLA-4, CiTEs overcome immune suppression within the tumor microenvironment and restore T-cell activation." (PMID 39982231, 2025). "These inhibitors work by blocking CTLA-4, thus boosting the immune system’s ability to target and destroy tumor cells." (PMID 40739089, 2025). "Dual blockade of PD-1 and CTLA-4 in murine K7M2 models achieved superior tumor control and increased intratumoral CD8+ T cell infiltration compared to monotherapy." (PMID 41244900, 2025). "Enhancing anti-tumor immunity and improving outcomes can be achieved by combining PD-1/PD-L1 inhibitors with other therapies, i.e., CTLA-4 and anti-VEGF antibodies." (PMID 40869156, 2025). "In combination with bevacizumab, anti-CTLA-4 enhanced tumor infiltration by promoting E-Selectin, ICAM-1 and VCAM-1 at the surface of melanoma cells." (PMID 40071851, 2025). "Our findings are consistent with those of other studies.For example, in tumor-associated B cells, STAT3 promotes CTLA4 expression in a JAK-dependent mechanism, while in Treg cells, STAT3 promotes CTLA4 expression via IL-10." (PMID 40092547, 2025). "ICIs target key regulatory pathways including programmed cell death protein 1 (PD-1), its ligands PD-L1 and PD-L2, and cytotoxic T-lymphocyte-associated protein 4 (CTLA-4), thereby enhancing CD8+ T-cell-mediated cytotoxicity against tumor cells." (PMID 40807168, 2025).
tumor (continued). "ICIs activate T-cell-mediated antitumor responses by blocking tumor immune evasion mechanisms, such as PD-1/PD-L1 and CTLA-4 inhibitors." (PMID 40018039, 2025). "PD-L1, PD-1, or CTLA-4 monoclonal antibodies can block tumor immune escape and restore the anticancer function of the autoimmune system." (PMID 40376001, 2025). "Secondly, dual blockade of CTLA-4 and PD-1 interacts with tumor-infiltrating lymphocytes (TILs) through distinct but complementary mechanisms, which can transform the immunosuppressive TME." (PMID 41583427, 2025). "Elevated CTLA4 and LAG3 expression reflects increased immune checkpoint activity, likely contributing to T cell exhaustion and immune suppression in the tumor microenvironment of high-risk patients." (PMID 40243888, 2025). "In several murine models, various ACT approaches, with PD-1/PD-L1 and CTLA-4 blockade, have been observed to induce tumor regression." (PMID 40075727, 2025). "Given the limited efficacy of conventional ICIs targeting PD-1, PD-L1, and CTLA-4 in mUM, there is an urgent need to explore novel immune regulatory pathways that contribute to tumor immune evasion." (PMID 40725830, 2025). "PD-1 and CTLA-4 can have context-dependent roles in immune regulation, potentially contributing to both immune suppression and tumor progression." (PMID 41203944, 2025). "Treg-specific CTLA4 knockout reduces tumor volume by 60% and increases CD8+ T cell infiltration by 3-fold in mice." (PMID 41415289, 2025). "Even when using CTLA-4 and PD-L1 inhibitors, immunosuppressive cells in the tumor microenvironment (such as MDSCs and Tregs) can hinder T-cell activity by secreting immunosuppressive factors like TGF-β and IL-10, allowing tumors to evade immune attack." (PMID 39911393, 2025). "Given that rAd.sT.GM consistently inhibits both tumor growth and metastasis, we proceeded to test its efficacy in combination with anti-PD-1 (P) and anti-CTLA-4 (C) antibodies." (PMID 40104170, 2025). "Specifically, LIGHT activates T cells, while the anti-CTLA-4 antibody reverses the exhaustion state of activated T cells and eliminates inhibitory immune cells, thereby achieving effective control of tumor growth." (PMID 41346580, 2025). "Treg cells can restrict the activity of antigen-presenting cells by downregulating the expression of CD80 and CD86 in a CTLA4-dependent way, therefore preventing the presentation of tumor antigens and the activation of tumor-specific T cells." (PMID 41019045, 2025). "This construct effectively blocked the coinhibitory signaling pathways of PD-1 and CTLA-4, resulting in significant tumor growth suppression and TME remodeling in hCTLA-4/hPD-1 transgenic C57BL/6 mouse models." (PMID 40474230, 2025). "Our work revealed that LAG3, TIM3, and CTLA4 are crucial ICPs on iNKT cells favoring immune escape and tumor progression." (PMID 41562072, 2025). "Immune checkpoint molecules, including PD1, LAG3, and CTLA4, are crucial to regulate the T cells function in the tumor microenvironment." (PMID 40481915, 2025). "As CTLA-4 plays an important role in driving regulatory T cells, blocking it increases the intra-tumoral immune response by attenuating tumor-infiltrating regulatory T cells." (PMID 40821119, 2025). "Nanomaterials can serve as targeted delivery platforms for immune checkpoint inhibitors (such as antibodies against PD-1, PD-L1, and CTLA-4), enabling their precise localization within the tumor microenvironment and enhancing antitumor immune responses." (PMID 41142435, 2025). "Tumor expression of VISTA increases after anti-PD-1 or anti-CTLA-4 treatment; for example, 43% of patients treated with anti-PD-1 monotherapy relapsed within 3 years due to acquired resistance with high VISTA tumor expression." (PMID 40416959, 2025). "It enhances tumor antigen release and potentially increases the effectiveness of ICIs that block inhibitory pathways, such as PD-1/PD-L1 and CTLA-4, and restores T-cell activity against tumor cells." (PMID 40361336, 2025).